CRP (C-reactive protein)
Diseases named in the same sentence as CRP in open-access papers (continued):
Sharing a sentence is not in itself a finding about the gene and the disease.
periodontal disease (continued). "Some inflammatory mediators associated with periodontal disease, e.g. C Reactive Protein (CRP), Interleukin 6 (IL 6), Interleukin 1(IL 1β), and TNF-α have been suggested to increase the risk of cognitive decline and/or Alzheimer’s disease." (PMID 25516763, 2014). "Serum biomarkers of inflammation including IL-6, CRP and sICAM-1 have been associated with periodontal disease and COPD morbidity." (PMID 23950871, 2013). "Elevated levels of CRP are associated with infection by subgingival organisms related to periodontal disease, including Porphyromonas gingivalis and Prevotella intermedia." (PMID 22203908, 2011). "They concluded that extensive periodontal disease and body mass index (BMI) are associated with increased CRP levels in otherwise healthy, middle-aged adults." (PMID 21219642, 2011). "Circulating C-reactive protein (CRP) levels are a marker of systemic inflammation and are associated with periodontal disease, a chronic bacterial infection associated with elevation of proinflammatory cytokines and prostaglandins." (PMID 20379412, 2009). "There are very few studies to evaluate the association between periodontal disease and CRP levels in pregnant women." (PMID 20379412, 2009). "CRP, an acute-phase reactant synthesized by hepatocytes in response to pro-inflammatory cytokines such as interleukin-6 and tumor necrosis factor-alpha, is a key biomarker of systemic inflammation associated with periodontal disease." (PMID 39859455, 2025). "Therefore, hs-CRP findings were interpreted as reflecting chronic systemic inflammatory activity linked to periodontal disease, whereas conventional CRP results were used primarily to document overt inflammatory responses." (PMID 41294894, 2025). "It is possible that immunosenescence and inflammaging may be underlying reasons for the high periodontal disease burden and slightly elevated CRP values observed in our patients, in contrast to those described in younger populations." (PMID 38804312, 2024). "Periodontal disease has been found to be associated with elevated CRP levels." (PMID 38535432, 2024). "Similarly, elevated levels of C-reactive protein (CRP), an established marker of acute and chronic inflammation, strongly indicate the presence of destructive periodontal disease and inevitable tooth loss." (PMID 38066835, 2023). "This suggests that D. invisus abundance in the gut could be a proxy for abundance in the oral cavity, where it is known to be related to periodontal disease, which is itself associated with CRP." (PMID 36827280, 2023). "Previous studies have shown that elevated levels of serum inflammatory markers, such as tumor necrosis factor-α, interleukin-6, interleukin-2, and C-reactive protein, are associated with an increased risk of AF and are commonly found in patients with periodontal disease." (PMID 37420240, 2023). "Furthermore, the association between periodontal disease and CRP levels has already been established." (PMID 36471165, 2022). "This study aimed to assess the association between periodontal diseases and cardiovascular risk in a group of adult women, based on serum hs-CRP levels; and secondly, to determine the association between serum and gingival crevicular fluid CRP levels." (PMID 34439905, 2021). "The only dental variables that had a statistically significant association with CRP were periodontal disease (likelihood ratio Chi-square: 6.77), the number of teeth that required crowns (likelihood ratio Chi-square: 5.24), and missing teeth (likelihood ratio Chi-square: 36.91)." (PMID 33419028, 2021). "Second, this study targeted acute ischemic stroke patients, and various factors, such as systemic inflammation involving CRP or several cytokines, might therefore affect the association between serum antibody titers and both periodontal disease and CSVD." (PMID 33031428, 2020).
periodontal disease (continued). "Periodontal disease may be associated with more bacteria and consequent induction of a systemic inflammatory process, with changes in the levels of C-reactive protein (CRP)." (PMID 32994872, 2020). "Some studies have identified an increased level of plasma C-reactive protein in persons with periodontal disease, while others have linked periodontal disease with chronic inflammation, such as cardiovascular disease and cancers of the kidney, pancreas, and lung." (PMID 32570864, 2020). "As a chronic inflammation caused by periodontal pathogen infections, periodontal disease could increase the levels of C-reactive protein, IL-6, IFN-γ, and IL-1β." (PMID 32802852, 2020). "There is a positive relationship between salivary CRP and periodontal disease, which could help to explain the underlying link between periodontal disease and higher risk for CAD." (PMID 22152006, 2011). "This raises the possibility that CRP may mediate association between periodontal disease and preterm delivery." (PMID 20379412, 2009). "According to these authors, the higher prevalence of periodontal disease in Macaca mulatta with MS, associated with increased levels of C-reactive protein, suggests that chronic inflammation of the oral cavity may contribute to the activation of systemic inflammatory responses." (PMID 40872734, 2025). "Quantitative findings showed higher blood pressure, increased C-reactive protein levels, greater autoantibody positivity, enhanced inflammasome activity, and reduced oral microbiome diversity in individuals with periodontal disease." (PMID 41948248, 2026). "A raised quantity of inflammatory features, e.g., C-reactive protein (CRP) and fibrinogen, have been noted in individuals with periodontal disorders." (PMID 40091902, 2025). "This study is the first in assessing the combined predictive capacity of CRP eGFR in periodontal disease accounting for both oral and systemic diseases." (PMID 39859455, 2025). "Periodontal diseases contribute to systemic health issues by triggering chronic inflammation, as evidenced by elevated levels of biomarkers like C-reactive protein (CRP), interleukin-6 (IL-6), and tumor necrosis factor-alpha (TNF-α)." (PMID 40418274, 2025). "Another study reported that the periodontal disease severity affected the CRP levels and renal function and that CRP levels decreased after periodontal treatment." (PMID 40552326, 2025). "Elevated levels of C-reactive protein (CRP), a marker of systemic inflammation, are often seen in individuals with periodontal disease, further linking inflammation to the progression of the condition." (PMID 40075856, 2025). "The association between the CRP, NLR, PLR, and SII has been identified as providing relevant data regarding periodontal diseases and, moreover, in peri-implantitis." (PMID 41301163, 2025). "Utilizing structural equation modeling, we identified significant mediating effects of body mass index (19.58%), C-reactive protein levels (11.61%), blood glucose (6.70%), and healthy diet score (5.99%) between periodontal disease and PDFF (P for all <0.05)." (PMID 40270511, 2025). "Periodontal disease is associated with elevated inflammatory biomarkers, including IL-1, IL-6, TNF-α, and CRP, which are also elevated in AD." (PMID 40559320, 2025). "Inflammatory Markers: Periodontal disease can lead to elevated levels of systemic inflammatory markers such as C-reactive protein (CRP), tumor necrosis factor-alpha (TNF-α), and various interleukins (IL-1, IL-6, IL-8)." (PMID 39610974, 2024). "They intake more sugar, have fewer dental caries restorations and higher CRP levels, have periodontal diseases, have more untreated dental caries, and have fewer teeth." (PMID 38698375, 2024). "For instance, impairment in glucose tolerance is associated with a significant increase in the interleukin-6 and CRP levels, and the prevalence of periodontal disease in patients with DM was found to be higher than that of healthy controls." (PMID 39453923, 2024).
periodontal disease (continued). "There is a high periodontal disease burden in these patients, despite the exclusion of a possible influence of acute or chronic inflammation reflected by hematological C-reactive protein ≤ 5 mg/dL." (PMID 38804312, 2024). "Salivary nitric oxide inhibits decay, reduces periodontal disease, lowers CRP, and potentially affects airway resistance." (PMID 39065175, 2024). "By including only systemically healthy subjects, the impact of periodontal disease on CRP levels and consequently the systemic burden should be estimated quite accurately." (PMID 38652288, 2024). "C-reactive protein (CRP) is an acute-phase marker for inflammation produced in response to many forms of tissue injury and associated with periodontal diseases." (PMID 38433948, 2024). "Periodontal disease (PD) contributes to systemic inflammation by releasing mediators such as C-reactive protein (CRP), interleukins (IL-1, IL-6), tumor necrosis factor (TNF)-α, and α-1-antichymotrypsin into the body's circulation." (PMID 39044527, 2024). "This study was therefore interested in examining the potential relationship between CRP and periodontal disease in updated National Health and Nutrition Examination Survey (NHANES) data from 2009 to 2010." (PMID 37481511, 2023). "In this regard, a recent meta-analysis showed increased concentrations of CRP plasma in individuals affected by periodontal disease compared to healthy patients." (PMID 37214190, 2023). "Within the limitations of the current study, it can be suggested that destructive periodontal diseases contribute to systemic inflammatory response, as indicated by the levels of CRP in serum." (PMID 37568846, 2023). "PCOS was linked to increased levels of CRP, interleukin-6, and TNF- α, all of which contribute to chronic low-grade inflammation and raise the risk of periodontal disease." (PMID 38021744, 2023). "Serum CRP levels in patients with periodontal disease are higher, according to current findings based on systematic review." (PMID 37568846, 2023). "A correlation between C-reactive protein levels and periodontal disease was found in one cross-sectional study of the U.S. population older than two months using data from 1988 to 1994." (PMID 37481511, 2023). "CRP is a periodontal disease indicator, and it increases by several folds in response to infection or inflammation." (PMID 37568846, 2023). "Known biomarkers for periodontal disease include CRP, IL-1β, TGF-β, VEGF, proteolytic degradation products (CTx), and matrix metalloproteinases (MMPs)." (PMID 37262024, 2023). "CRP plasma concentrations are increased in subjects affected by the periodontal disease due to several studies carried out on populations even on a large scale in different continents; CRP has several biological functions relevant to the pathogenesis of CVD." (PMID 37214190, 2023). "In some inflammatory, infective, and ischemic disorders, such as periodontal disease, serum CRP has also been used as a measure of disease activity and response to therapy." (PMID 37568846, 2023). "According to NHANES III data, a cross-sectional investigation of the US population revealed a link between periodontal disease and CRP." (PMID 37481511, 2023). "Similar inflammatory mediators, such as IL-6, TNF- α, and CRP, are increased in patients with severe periodontal disease (PD)." (PMID 36361416, 2022). "Similar inflammatory mediators, such as interleukin-6, tumor necrosis factor-alpha, and C-reactive protein, are increased in patients with severe periodontal disease." (PMID 36361416, 2022). "There were significant differences in sex (p = 0.032), BMI (p = 0.001), number of teeth (p < 0.001), ABL (p < 0.001), hs-CRP (p < 0.001), and periodontal disease severity classification (p < 0.001) between the type 2 diabetic group and the non-diabetic group." (PMID 35805792, 2022).
periodontal disease (continued). "Therefore, the present study may have included dogs with a more severe periodontal condition than that previously reported, which correlated with results of many blood tests, suggesting that the expansion of periodontal disease causes systemic inflammation as indicated with CRP and Glob data." (PMID 34980120, 2022). "Certain studies have revealed that periodontal disease increased systemic inflammation markers, including C-reactive protein (CRP), cytokines and chemokines." (PMID 35881627, 2022). "We aimed to assess the association between periodontal diseases and CVR in a group of adult women, based on serum high-sensitivity CRP (hs-CRP) levels; and secondly, to determine the association between serum and GCF CRP levels." (PMID 34439905, 2021). "Compared with that of healthy individuals, patients with periodontal disease present with significantly increased serum CRP levels." (PMID 34262126, 2021). "Regarding oral disease, the intensity of gingival inflammation is proportional to the intensity of the systemic response, as measured by C-reactive protein levels in a study of dogs with periodontal disease." (PMID 33059691, 2020). "In previous research, the correlation between periodontal disease and CRP level was analyzed in a dichotomous manner." (PMID 33424972, 2020). "At the same time, CRP, a long-known inflammatory indicator presenting increased levels in periodontal disease (plasma as well as salivary levels), after anti-inflammatory treatment displays decreased levels, which is an indicator of a successful treatment." (PMID 32685098, 2020). "Studies have shown that with periodontal disease, there is an increase in inflammation markers, like IL-6 (Interleukin 6) and C-reactive protein (CRP) which were related to decreased physical capability and muscle strength in frail adults." (PMID 32858854, 2020). "Because low vitamin C correlated with more advanced periodontal disease and with increased CRP, a measure of systemic inflammation, it is likely that this finding is biologically important." (PMID 32731485, 2020). "Periodontal disease is correlated with increased concentrations of serum IL-1, IL-6, prostaglandin and C-reactive proteins (CRP)." (PMID 32218125, 2020). "Based on these results, we felt that hs-CRP was a better marker of the severity of periodontal disease and progression of the disease in HD patients than CRP." (PMID 31382656, 2019). "Further studies with more detailed analyses and larger populations are necessary to determine the pathological significance and value of CRP or hs-CRP levels as biomarkers in HD patients with periodontal disease." (PMID 31382656, 2019). "A clinical study also showed that the relationship between NAFLD and periodontal disease was modified by serum CRP concentration." (PMID 29760403, 2018). "In the present study, the results showed that serum CRP concentration tended to increase according to the severity of periodontal disease." (PMID 29760403, 2018). "Inflammatory biomarkers that have been found to be elevated in the saliva of adult individuals with T2D and periodontal disease include interleukin 1-β (IL-1β) and C-reactive protein (CRP)." (PMID 28253297, 2017). "Salivary levels of IL-1β, CRP and NO levels have been reported to be higher in patients with periodontal disease when compared to healthy dentate patients." (PMID 28253297, 2017). "Key words:Periodontal diseases, edentulousness, C reactive protein, cardiac troponin T, nitric oxide." (PMID 28578371, 2017). "To summarize, the diabetic patients with periodontal disease had significantly higher serum CRP, IL-6 and TNF-α values by comparison with healthy subjects." (PMID 26644840, 2015). "Patients with periodontal disease had significantly higher serum CRP, IL-6 and TNF-α values by comparison with healthy subjects." (PMID 26644840, 2015).
periodontal disease (continued). "Before melatonin treatment, serum TNF-α, IL-6 and CRP levels in diabetic patients with periodontal disease were significantly higher than in healthy control subjects." (PMID 26644840, 2015). "Novelty of obtained results was based on the comparison of four types of periodontal diseases, as usually two or three types are compared, and on comparison of diverse periodontal indices with subsequently established CRP levels in patient's peripheral blood." (PMID 26346216, 2015). "After a 20 days of daily local melatonin application in such diabetic patients with periodontal disease, a significant decrease in serum CRP and IL-6 levels as well as an improvement in the gingival index and pocket depth was observed." (PMID 26644840, 2015). "Positive correlation between CRP and periodontal disease severity was proved by many studies, and levels of CRP decrease after nonsurgical periodontal therapy." (PMID 26346216, 2015). "Our study results show that CRP levels increase subsequently with the severity of the periodontal disease." (PMID 26346216, 2015). "Many inflammatory mediators are known for early and comfortable diagnosis of periodontal disease, such as interleukins, c-reactive protein (CRP), lactate dehydrogenise (LDH) and more recently nitric oxide (NO)." (PMID 25317400, 2014). "The results of this study shows a significant correlation between salivary CRP levels and severity of periodontal disease." (PMID 24551806, 2013). "Our study showed that CRP levels also increased in parallel to the severity of periodontal diseases." (PMID 24551806, 2013). "Our study showed that the measurement of salivary CRP can be used as a non-invasive and reliable test for the detection and screening of periodontal disease in healthy people." (PMID 24551806, 2013). "Analysis of data collected in the NHANES III found a positive correlation between serum C-reactive protein (CRP) levels and the severity of periodontal disease." (PMID 23840952, 2013). "The aim of the present study was the comparison of the amount of salivary C-Reactive protein (CRP) in healthy subjects and patients with periodontal disease." (PMID 24551806, 2013). "High serum titre to P. gingivalis and the presence of periodontal disease are independently related to high C-reactive protein levels." (PMID 23308100, 2013). "Several investigations regarding the relationship between salivary CRP levels and periodontal disease have also been done." (PMID 24551806, 2013). "Bacterial pathogens causing periodontal disease incite the secretion of inflammatory mediators, including IL-6, TNF-α and CRP." (PMID 23951003, 2013). "Mean PPD and mean CAL are a pretty accurate ways of evaluating periodontal disease severity and these values were correlated with hs-CRP levels to find any relationship." (PMID 22322513, 2012). "The purpose of this study was to analyze how anti-infectious periodontal treatment affects CRP values in patients with type 1 diabetes and if baseline CRP levels are related to periodontal disease severity." (PMID 22322513, 2012). "The results of this cohort study demonstrated the elevated CRP levels in pregnant women with periodontal disease compared to healthy controls and preterm delivery rate was higher in women with periodontal disease compared to control group." (PMID 20379412, 2009). "Post-hoc pairwise comparison of adjusted mean showed a significantly higher mean CRP values (1.204 and 1.22) in periodontal disease groups compared to control group (0.713)." (PMID 20379412, 2009). "The mean value of C-reactive protein levels in subjects with periodontal disease was higher compared to control group i.e., 1.20 ± 0.247 mg/dl and 1.22 ± 0.250 mg/dl, respectively, compared to 0.713 ± 0.139 mg/ dl (P = 0.001)." (PMID 20379412, 2009).